SAMHD1 (SAM and HD domain containing deoxynucleoside triphosphate triphosphohydrolase 1)
Diseases named in the same sentence as SAMHD1 in open-access papers (continued):
Sharing a sentence is not in itself a finding about the gene and the disease.
lung adenocarcinoma (10 papers, 2013 to 2025). A carcinoma that arises from the lung and is characterized by the presence of malignant glandular epithelial cells. "The single-stranded DNA (ssDNA) accumulated in the cytosol of SAMHD1-deficient lung adenocarcinoma (LUAD) cells, accompanied by upregulated DNA sensor IFN-γ-inducible protein 16 (IFI16) and activated STING pathway." (PMID 36578072, 2022). "To explore the role of SAMHD1 in tumorigenesis, we first examined the SAMHD1 expression by immunohistochemistry in several early-stage (stages I and II) human cancers including colonic and lung adenocarcinomas as well as thyroid carcinoma." (PMID 37081042, 2023). "In contrast, cell proliferation in lung adenocarcinoma (LUAD) is suppressed by SAMHD1 overexpression." (PMID 37009792, 2023). "HCC827 lung adenocarcinoma cells exhibited the lowest SAMHD1 expression among CCLE-annotated solid tumor cells and were highly susceptible to PNPi/dG in a dCK-dependent manner." (PMID 35653193, 2022). "The roles of SAMHD1 in the activation of cytosolic DNA sensing STING pathway in lung adenocarcinoma (LUAD) cells were investigated with flow cytometry, immunofluorescence, immunoblotting and qPCR." (PMID 36578072, 2022). "SAMHD1 silencing also enhances apoptotic cell death in lung adenocarcinoma cells." (PMID 40434097, 2025). "Moreover, SAMHD1 downregulation combined with radiation enhances anti-tumor immune responses to lung adenocarcinoma in mice." (PMID 40434097, 2025). "Additionally, SAMHD1 expression seems to be downregulated, both on the mRNA and protein level, in malignant tissue from five lung adenocarcinoma (LAC) patients compared to the surrounding unaffected lung tissue." (PMID 34480199, 2022). "Again, the authors could correlate high SAMHD1 promoter methylation with lower SAMHD1 levels in lung adenocarcinoma." (PMID 34480199, 2022). "Additionally, downregulation of SAMHD1 expression has been reported in cutaneous T-cell lymphoma and lung adenocarcinoma." (PMID 33857133, 2021). "Subsequently, it is indicated that the overexpression of SAMHD1 can suppress the progression of lung adenocarcinoma (LUAD) by inhibiting the expression of STING and STING can be used as a potential downstream target of SAMHD1 in lung cancer after MTT assays and Transwell assays." (PMID 38566036, 2024). "TCGA analysis showed that SAMHD1 mRNA levels were much lower in tumor tissues than in nontumor tissues in several cancer types, such as colorectal adenocarcinoma, bladder urothelial carcinoma, lung adenocarcinoma, and lung squamous cell carcinoma." (PMID 37009792, 2023).
lung carcinoma (10 papers, 2015 to 2024). "Regarding disease association, reduced levels of SAMHD1 expression corresponded with SAMHD1 promoter methylation in lung cancer and patients with Sezary syndrome." (PMID 34925380, 2021). "Among them, CTNNB1, ZEB1, CDC42, HSP90AA1, BST2, PCNA, and E2F1 have all been shown to promote lung cancer progression, while SAMHD1, HRAS, and NQO1 serve as tumor suppressor genes." (PMID 28498804, 2017). "Similar effects of SAMHD1 promoter methylation on its expression were identified in lung cancer tissues." (PMID 26416562, 2015). "Overexpression of SAMHD1 in a lung cancer cell line results in decreased proliferation in vitro, with a concomitant increase in intracellular dNTP levels." (PMID 26416562, 2015). "Lung carcinoma patients have reduced SAMHD1 mRNA and protein, but a direct correlation to disease progression or outcome has not been established." (PMID 26416562, 2015). "Indeed, overexpression of SAMHD1 has been found to reduce the proliferation of A549 lung cancer cells." (PMID 36579897, 2023). "Consistent with this hypothesis, we also found increased SAMHD1 variation in individuals with lymphoid neoplasms, as well as with prostate, breast, colorectal, and lung cancers." (PMID 36199081, 2022). "We found that SAMHD1 silencing in lung cancer cells promoted macrophage M1 polarization, which might improve the tumor immune microenvironment." (PMID 36578072, 2022). "Interestingly, SAMHD1 displays a general downregulation in most cancer types, implying a correlation between cancer and SAMHD1 repression — with the strongest downregulation observed in lung cancers." (PMID 34480199, 2022). "Studies in lung cancer and CTCL patients have revealed the role of epigenetic mechanisms in downregulation of SAMHD1 expression." (PMID 26416562, 2015).
lupus (8 papers, 2015 to 2026). "LINE-1 activity is upregulated in cells deficient for TREX1, a gene associated with systemic lupus erythematosus (SLE) and, like SAMHD1, with AGS." (PMID 26001115, 2015). "Some single gene variants (SAMHD1, RNASEH2ABC, ADAR1, IFIH1, ISG15, ACP5, TMEM173) can cause monogenic lupus." (PMID 35783307, 2022). "Patients with SAMHD1 mutations can develop SLE, Aicardi–Goutières syndrome, and chilblain lupus." (PMID 37504294, 2023). "Other types of type-I interferonopathies, such as systemic lupus erythematosus (SLE) and Aicardi–Goutières syndrome (AGS), have relationships with defective clearance of cytosolic nucleic acids caused by congenital dysfunction of TREX1, RNASEH2, and SAMHD1." (PMID 32411126, 2020). "Familial chilblain lupus or TREX1-associated systemic lupus erythematosus is an autosomal dominant autoinflammatory disease caused by either loss-of-function mutations in TREX1 and SAMHD1 genes or gain-of-function mutations in the TMEM173 gene, both leading to type I IFN overproduction." (PMID 31736939, 2019).
COVID-19 (7 papers, 2020 to 2025). A disease caused by infection with severe acute respiratory syndrome coronavirus 2. "We suggest that SAMHD1 is the molecule that may be behind the mechanisms of the neurological complications associated with COVID-19." (PMID 33101175, 2020). "It has been suggested that SAMHD1 may be associated with neurological complications of COVID-19." (PMID 35922752, 2022). "Meanwhile, SARS-CoV-2 host genes, such as ACTB, KPNA2, and JUN, interact with SAMHD1, VCAM1, and HMOX1, in the PPI network, indicating possible mechanisms of COVID-19 associated stroke." (PMID 33732102, 2021). "We correlate ACE2 to the pathogenesis and neurologic complications of COVID-19 and found that SAMHD1 links to NF-κB pathway." (PMID 33101175, 2020). "The top enriched clusters across SARS-CoV-2/COVID-19 studies included genes OAS1-3, IFIT3, SAMHD1, and MX1 involved in the innate immune response, interferon signaling, and defense response to the virus." (PMID 41227320, 2025). "Furthermore, the roles of other stroke-associated genes, such as SAMHD-1, DDAH-1, HMOX1, LTC4S, ACTB, KPNA2, and JUN, in mediating stroke secondary to SARS-CoV-2 infection are required to be further explored experimental using COVID-19 patient samples or SARS-CoV-2 animal models." (PMID 33732102, 2021). "Finally, suppression of the viral response genes (MX1 (p < 0.05), SAMHD1 (p < 0.001), IFITM3 (ns)) occurred more in severe ventilation-associated COVID-19 cases compared to non-ventilated cases." (PMID 33633121, 2021). "With non-severe (non-ICU) COVID-19, there was increased expression of the viral entry gene (CTSL (p < 0.05)) and increased antiviral response genes (MX1 (p < 0.0001), SAMHD1 (p < 0.0001), TRIM25 (p < 0.01), IFITM3 (ns))." (PMID 33633121, 2021). "For patients with COVID-19 who were not admitted to ICU, there was a statistically significant relationship between viral defense genes and CTSL expression, the four predictors (MX1, TRIM25 SAMHD1 and IFITM3) accounted for 65.56% of the variance (adjusted R2 = 0.656, p-value = 8.796–11)." (PMID 33633121, 2021).
HCMV infection (7 papers, 2020 to 2025). "SAMHD1 loss during the late stages of HCMV infection was further investigated by IFA." (PMID 32850489, 2020). "In return, HCMV infection suppresses SAMHD1 expression transcriptionally and promotes SAMHD1 protein proteasomal degradation." (PMID 40277359, 2025). "Hyeon and colleagues also analyzed SAMHD1 protein level and found that HCMV infection induces the proteasomal degradation of SAMHD1 via a Cullin2 E3 ubiquitin ligase complex." (PMID 33801276, 2021). "SAMHD1 was shown to be strongly phosphorylated at the regulatory T592 site upon HCMV infection, as well as upon transient pUL97 coexpression." (PMID 33801276, 2021). "Taken together, these results indicate that both the viral protein kinase pUL97 and the cellular kinase Cdk2 were involved in SAMHD1 T592 phosphorylation during HCMV infection." (PMID 32986788, 2020). "We also found that the level of SAMHD1 was initially increased by HCMV infection but decreased partly at the protein level at late stages of infection." (PMID 32850489, 2020). "In the present study, we demonstrate that SAMHD1 expression was increased following human cytomegalovirus (HCMV) infection, with only a modest effect on infectious virus production." (PMID 32986788, 2020). "We also showed that expression of SAMHD1 is downregulated at late stages of HCMV infection at both transcription and protein levels, and that regulation at the protein level requires the CRL activity." (PMID 32850489, 2020). "Altogether, these results indicate that SAMHD1 is rapidly upregulated at both the mRNA and protein level upon HCMV infection with most viral strain-cell type combinations tested." (PMID 32986788, 2020). "To study the role of SAMHD1 in HCMV infection, we first investigated if its expression was modulated at both mRNA and protein levels in different cell types." (PMID 32986788, 2020). "In this study, we addressed the role of SAMHD1 in HCMV infection by investigating its expression levels and phosphorylation status after infection of different cellular models with distinct HCMV strains." (PMID 32986788, 2020). "HCMV infection (multiplicity of infection, MOI 1 PFU/ml) of HFFs caused a significant upregulation of SAMHD1 mRNA levels by 1 and 2 dpi, compared to mock-infected HFFs." (PMID 32986788, 2020). "Here, we investigated the regulation of SAMHD1 expression during human cytomegalovirus (HCMV) infection." (PMID 32850489, 2020). "Nevertheless, we hypothesized that despite the significant increase in SAMHD1 expression levels detected upon HCMV infection, its modest antiviral activity could be due to inactivation by T592 phosphorylation." (PMID 32986788, 2020). "Notably, SAMHD1 was also upregulated by ~5 fold upon HCMV infection of differentiated THP-1 macrophage-like cells, which are considered a physiologically important target for HCMV infection." (PMID 32986788, 2020). "When we compared SAMHD1 protein levels at different MOIs (0.5 and 3), SAMHD1 loss occurred at 96 h at an MOI of 0.5, while it was observed as early as 48 h at an MOI of 3, indicating that when SAMHD1 loss is observed after HCMV infection depends on MOIs." (PMID 32850489, 2020). "Expression of SAMHD1 and its phosphorylation are initially increased during HCMV infection." (PMID 32850489, 2020). "We thus investigated SAMHD1 ability to counteract HCMV infection." (PMID 32986788, 2020). "To further investigate the mechanism by which SAMHD1 is lost during HCMV infection, we compared the effects of MG132, MLN4924, and bafilomycin A1, a specific and potent inhibitor of vacuolar-type H+-ATPases that blocks lysosomal degradation, on CRL-mediated SAMHD1 loss." (PMID 32850489, 2020). "The unprecedented observation of relocation of phosphoT592-SAMHD1 outside the nucleus may affect SAMHD1 function upon HCMV infection, and thus might represent a novel HCMV-mediated immune evasion strategy that will need further investigations." (PMID 32986788, 2020).
HCMV infection (continued). "These IFA results demonstrate that the nuclear SAMHD1 level is reduced and its distribution is changed at late times of HCMV infection in a manner partly dependent on the CRL activity, supporting the finding that SAMHD1 is lost in a CRL-dependent manner during the late stages of HCMV infection." (PMID 32850489, 2020). "We investigated how SAMHD1 expression is regulated during HCMV infection." (PMID 32850489, 2020). "We next evaluated the impact of HCMV infection on SAMHD1 localization, with the rationale that the inability of SAMHD1 to restrict HCMV replication may relate to a viral evasion mechanism that altered the nuclear localization of SAMHD1, which contains a classic nuclear localization signal (NLS)." (PMID 32986788, 2020). "Although less investigated in the context of CMV infection, RNR activation probably plays an equally important role as SAMHD1 inhibition for virus growth." (PMID 34903047, 2021). "Therefore, to gain further insights into HCMV-induced SAMHD1 phosphorylation, we next asked whether Cdk1/2 were involved in T592 phosphorylation in response to HCMV infection, since cellular cyclin A2/Cdk1/2 complexes have been shown to phosphorylate SAMHD1 at T592." (PMID 32986788, 2020). "In addition, Businger and colleagues observed that the SAMHD1-mediated restriction of HCMV is potently antagonized by the viral kinase pUL97, as well as by activation of cellular CDKs following HCMV infection." (PMID 33801276, 2021). "Interestingly, studies found that latent HCMV infection of CD34+ progenitor cells downregulated expression of various HIV-1 restriction factors, including SAMHD1, APOBEC3G, and Mx2, while upregulating the expression of HIV-1 coreceptors CXCR4 and CCR5." (PMID 32244340, 2020).
Stroke (7 papers, 2010 to 2023). Sudden impairment of blood flow to a part of the brain due to occlusion or rupture of an artery to the brain. "SAMHD1 mutations result in atherosclerotic changes in major vessels, predisposing people to early stroke." (PMID 33447134, 2020). "Mutations in SAMHD1, a dNTPase known to be important for innate immunity, have been shown to lead to cerebral vasculopathy and early onset stroke." (PMID 32300291, 2020). "The present study revealed that SAMHD1 gene mutations are associated with LAA in a Chinese stroke cohort." (PMID 26504826, 2015). "We conclude that cerebrovascular stenoses and stroke associated with the Arg164X mutation in SAMHD1 extend the phenotypic spectrum of AGS." (PMID 20842748, 2010). "In summary, the Arg164X mutation in SAMHD1 was associated with stenoses of intracranial vessels, stroke, and glaucoma, a finding extending the phenotype of AGS." (PMID 20842748, 2010). "In this study, we investigated this hypothesis in a stroke cohort with a completely different ethnic background from that of the original studies linking SAMHD1 mutations to cerebral vasculopathy." (PMID 26504826, 2015). "The exact mechanism of how the SAMHD1 mutations serve as a genetic predisposition for stroke remains unclear." (PMID 26504826, 2015). "Heterozygous SAMHD1 gene mutations might cause genetic predispositions that interact with other risk factors, resulting in increased vulnerability to stroke." (PMID 26504826, 2015). "However, it should be noted that, along with SAMHD1 mutations, multiple stroke risk factors, such as hypertension, hyperlipidaemia, hyperhomocysteinaemia, and alcohol and tobacco use, were also identified in all three patients." (PMID 26504826, 2015). "Considering the roles of the SAMHD1 gene in human innate immunity, the clinical findings of monogenic linkage studies, and its unique structural requirement for catalytic and biological activity, we hypothesised that the SAMHD1 gene may be associated with stroke in the general population." (PMID 26504826, 2015). "Thus, we suggest that SAMHD1 mutations might create a genetic predisposition for stroke that leads to an increased vulnerability to stroke in those patients by interacting with other risk factors." (PMID 26504826, 2015). "Along this line, our dataset shows an induction of SAMHD1 in the postacute phase suggesting a potential role for SAMHD1 in post-stroke vascular repair and regeneration." (PMID 32300291, 2020). "Further studies involving additional patient populations and exploring the mechanism underlying the effect of SAMHD1 mutations on the development of LAA in the general population will be valuable, not only for patients who are directly affected but also for stroke patients in general." (PMID 26504826, 2015).
acute lymphoblastic leukaemia (6 papers, 2015 to 2025). "The damaging variants in SAMHD1 that we identified are associated with increased risk of ‘all cancer’ in men and women, as well as in sex-specific cancers, highlighting SAMHD1 as a novel risk factor for prostate cancer in men and hormone-sensitive cancers in women." (PMID 39261734, 2024). "Moreover, SAMHD1 expression levels determine acute lymphoblastic leukemia cell response to nelarabine." (PMID 37081042, 2023). "SAMHD1, a recently identified nuclear protein restriction factor, is highly expressed in HIV-1 non-permissive cells, whereas it is absent from HIV-1-sensitive T-cell lines such as Jurkat, SupT1, human peripheral blood acute lymphoid leukemia, and U937." (PMID 25890101, 2015). "IMPDHi synergized with ara-C and F-ara-A in a SAMHD1-dependent manner in a subset of AML cells, but not in acute lymphoblastic leukaemia cell lines." (PMID 41399259, 2025).
lentivirus infection (6 papers, 2012 to 2025). Virus diseases caused by the Lentivirus genus. "Given the requirement for reverse transcription, we tested whether the cytosolic DNA-sensing pathway detects lentivirus infection in SAMHD1-deficient myeloid cells." (PMID 27477283, 2016). "To circumvent SAMHD1 (sterile alpha-motif domain and His-Asp domain-containing protein 1)-mediated restriction of lentivirus infection of human monocytes, we generated lentivirus particles containing Vpx." (PMID 27636895, 2016). "In sum, these observations provide genetic evidence that cGAS, STING, and signaling through the type I IFN receptor are required for SAMHD1-dependent myeloid cell activation upon lentivirus infection." (PMID 27477283, 2016). "We provide genetic evidence that cell-autonomous control of lentivirus infection in myeloid cells by SAMHD1 limits virus-induced production of IFNs and the induction of co-stimulatory markers." (PMID 27477283, 2016). "Taken together, these data provide direct genetic evidence that SAMHD1-mediated restriction impedes detection of lentivirus infection in myeloid cells." (PMID 27477283, 2016). "Experimental evidence supports a model in which SAMHD1 inhibits primate lentivirus infection in quiescent cells by depleting dNTP levels below the threshold required for viral reverse transcriptase to efficiently synthesize proviral cDNA." (PMID 23426366, 2013). "It has been demonstrated that SIV-Vpx relieves the inhibition of lentivirus infection leading to highly efficient proteasome-dependent degradation of the protein SAMHD1." (PMID 22913641, 2012). "SAMHD1 and the HUSH complex constitute two blocks during primate lentivirus infection, the first by limiting reverse transcription and the second by inhibiting proviral expression." (PMID 40261013, 2025). "Our study provides genetic and in vivo data that the restriction factor SAMHD1 does not operate in conjunction with other innate and adaptive immune responses to ensure control of lentivirus infection." (PMID 27477283, 2016). "Whereas a functional HD domain is essential for the ability of SAMHD1 to inhibit primate lentivirus infection in nondividing cells, the roles of other SAMHD1 domains are not well established." (PMID 23426366, 2013).